ROBO1 (roundabout guidance receptor 1)
Diseases named in the same sentence as ROBO1 in open-access papers (continued):
Sharing a sentence is not in itself a finding about the gene and the disease.
gastric cancer (19 papers, 2010 to 2025). A primary or metastatic malignant neoplasm involving the stomach. "For example, elevated expression of miR-29a, along with suppression of its target gene Robo1, may serve as a diagnostic or therapeutic target in gastric cancer." (PMID 31455873, 2019). "The authors’ laboratory has led several leading researches that have specifically clarified the upstream mechanisms of SLIT2/ROBO1 in gastric cancer (GC) metastasis." (PMID 37443302, 2023). "USP33 stabilizes Robo1 by reducing the ubiquitination of Robo1, thus is required for the Slit2‐Robo1 signalling in inhibiting gastric cancer cell migration and EMT." (PMID 30896071, 2019). "Tumor suppressive function of miR-218 was also reported in several types of cancer targeting several oncogenic genes, such as RICTOR (oral cancer), survivin and ROBO1 (nasopharyngeal cancer), and ROBO1 (gastric cancer)." (PMID 23159910, 2012). "It has been demonstrated that the restoration of miR-218 suppresses Robo1 expression and inhibits gastric cancer cell invasion and metastasis in vitro and in vivo." (PMID 22860003, 2012). "The inverse relationship between miR-218 and Robo1 expression was further confirmed by immunohistochemistry in 40 cases of gastric cancer, in matched adjacent normal tissues that were also used in clinicopathological studies, and in 29 matched metastases." (PMID 20300657, 2010). "Interestingly, Pou2f2 has been identified in a Nf-kB/Pou2f2/Robo1/Slit2 signaling cascade that promotes metastasis in gastric cancer cells." (PMID 31787878, 2019). "MiRNA-218 inhibited gastric cancer angiogenesis and metastasis by downregulating ROBO1." (PMID 29383201, 2017). "SLIT2, an axon guidance protein produced by CAFs, promotes metastasis of gastric cancer cell lines AGS and MKN45 by binding to the roundabout guidance receptor 1 (ROBO1)." (PMID 39850884, 2024). "The present study demonstrated that SLIT2, an axon guidance protein, produced by CAFs and promoted gastric cancer (GC) metastasis in two gastric cancer cell lines (AGS and MKN45) by binding to roundabout guidance receptor 1 (ROBO1)." (PMID 37443302, 2023). "In gastric cancer, two targets of miR-218 have been identified: Angiopoietin-2 and ROBO1 (roundabout guidance receptor 1); their downregulation results in a reduction of tumor proliferation, invasion, and angiogenesis." (PMID 31757094, 2019). "Slit2, Robo1 and USP33 expressions were analysed in datasets obtained from the Oncomine database and measured in human gastric cancer specimens." (PMID 30896071, 2019).
hepatocellular carcinoma (19 papers, 2013 to 2025). A malignant tumor that arises from hepatocytes. "For example, nanoparticles delivery si-circ-ROBO1 to hepatocellular carcinoma cells circ-ROBO1 inhibited tumor progression by modulating circ-ROBO1/miR-130a-5p/CCNT2 Axis." (PMID 37525158, 2023). "Genetic suppression of Slit2 or overexpression of Robo1 in hepatocellular carcinoma promotes tumor growth and metastasis." (PMID 35838343, 2023). "We have developed an anti-Robo1 monoclonal antibody and showed the antitumor effects of an isotope-labelled version of this antibody against hepatocellular carcinoma and small cell lung cancer xenografts." (PMID 32256588, 2020). "SLIT2 upregulated pathological condition of hepatocellular carcinoma shows a higher expression of ROBO1." (PMID 32760720, 2020). "miR-490-5p inhibits cell proliferation, migration and invasion but miR-490-5p can promote apoptosis of Human hepatoma (Hep3B) cells by inhibiting Roundabout Guidance Receptor 1 (ROBO1)." (PMID 30971240, 2019). "ROBO1 is up-regulated in hepatocellular carcinoma and colorectal cancer, which indicates its oncogenic role in these cancers." (PMID 26610476, 2015). "In this study, we examined biodistribution and radioimmunotherapy (RIT) using a radioisotope-labelled anti-ROBO1 monoclonal antibody (MAb) against hepatocellular carcinoma models." (PMID 25006547, 2014). "ROBO1 expression was significantly increased in prostate tumors and hepatocellular carcinoma as compared to normal tissue." (PMID 23593148, 2013). "In addition, using hepatocellular carcinoma PDXs and lung cancer cases 1 and 2 PDXs, we established a system for simultaneously staining five membrane protein common cancer antigens EphB4, ROBO1, LAT1, CLDN1, GPC3, and HLA class I in six colors." (PMID 40076777, 2025). "Moreover, previous studies have confirmed that SLIT2 knockdown can induce the over-expression of ROBO1 in hepatocellular carcinoma." (PMID 37059586, 2023). "MicroRNA-588 and its potential target Roundabout-directed receptor 1 (ROBO1) have been reported to promote tumor invasion and proliferation in diseases such as gastric, pancreatic and hepatocellular carcinoma, while their function in GBM and response to hypoxic states remain elusive." (PMID 36459288, 2023). "Further, SLIT2 and ROBO1 were reported to promote the migration of hepatocellular carcinoma cells." (PMID 37059586, 2023). "Upregulated miR-29-3p could inhibit hepatocellular carcinoma cell proliferation, migration, invasion, and metastasis through inhibition of Robo1 and inactivation of the PI3K/Akt/mTOR signaling pathway." (PMID 36430972, 2022). "Robo1 was originally reported as a surface antigen of hepatocellular carcinoma." (PMID 32256588, 2020). "ROBO1-positive HepG2 human hepatocellular carcinoma xenograft nude mice were used in this study." (PMID 25006547, 2014). "ROBO1 contributes to tumour metastasis and angiogenesis and may have potential as a target protein of immunotherapy because ROBO1 is specifically expressed at high levels in hepatocellular carcinoma." (PMID 25006547, 2014). "ROBO1, like GPC3, has been identified as a membrane protein frequently expressed in hepatocellular carcinoma." (PMID 40076777, 2025). "Other investigators on the model of hepatocellular carcinoma (HCC) demonstrated, that Robo1 expression promoted tumor angiogenesis and may be considered as an alternative target for anti-angiogenesis treatment." (PMID 34445494, 2021). "We previously conducted an RIT study in hepatocellular carcinoma (HCC) targeting the ROBO1 antigen." (PMID 26017283, 2015). "The Cancer Genome Atlas (TCGA), Integrative Molecular Database of Hepatocellular Carcinoma (HCCDB), Human Protein Atlas (HPA) and Kaplan–Meier Plotter databases were used to evaluate miR-152-3p and roundabout guidance receptor 1 (ROBO1) expression, prognosis and immune infiltration." (PMID 35236289, 2022).
hepatocellular carcinoma (continued). "However, it was revealed that ROBO1 is frequently expressed on the cell membrane in hepatocellular carcinoma, pediatric cancer, lung squamous cell carcinoma, pharyngeal cancer, and esophageal cancer, suggesting that CAR-T cell therapy targeting ROBO1 may be effective against these cancer types." (PMID 40076777, 2025). "In hepatocellular carcinoma, LAT1 is not expressed, but instead, ROBO1 is expressed at high frequencies." (PMID 40076777, 2025).
lung carcinoma (19 papers, 2005 to 2025). "In the lung, Slit/Robo suppresses tumor formation, and Robo1−/− and Robo1+/− mice have a high incidence of alveolar hyperplasia and exhibit increased susceptibility to lung cancer." (PMID 37513116, 2023). "From the non-lung cancer dataset, 113 variants of ROBO1, 134 variants of SLIT2 and 41 variants of ROBO4 were selected for structure-based analysis." (PMID 33318575, 2020). "Robo1-deficient mice exhibit bronchial epithelial hyperplasia and focal dysplasia, pathological features associated with early-stage lung cancer." (PMID 24981056, 2014). "Thus, from the lung cancer dataset, 18 variants of ROBO1, 29 variants of SLIT2 and 13 variants of ROBO4 were selected for structure-based analysis." (PMID 33318575, 2020). "This work aims at the in silico prioritisation, and pathogenicity assessment of the missense variants of SLIT2/ROBO1/4 reported in lung cancer cases, based on sequence- and structure-based parameters followed by docking analyses to determine the interaction dynamics." (PMID 33318575, 2020). "Similarly, in the non-lung cancer dataset, 5 variants of ROBO1.IG1, 7 variants of SLIT2.D2 and 2 variants of ROBO4.IG1-2 domains show an inter-orbit shift of mutant amino acid compared to wild types." (PMID 33318575, 2020). "It was reported that the silence of the SLIT2/ROBO1 signaling pathway was involved in the progression of several malignancies, including gastric, pancreatic,and lung cancer." (PMID 35615148, 2022). "The cognate interaction of ROBO1/4 with its ligand SLIT2 is known to be involved in lung cancer progression." (PMID 33318575, 2020). "About 61% of ROBO1, 45% of ROBO4, and 61% of SLIT2 variants of non-lung cancer dataset were predicted to be "damaging" by SIFT." (PMID 33318575, 2020). "PolyPhen243 predicted about 15% of ROBO1, 15% of ROBO4, and 23% of SLIT2 variants of lung cancer dataset to be "possibly damaging"." (PMID 33318575, 2020). "About, 0.4% of ROBO1, 0.8% of ROBO4, and 2% of SLIT2 variants of non-lung cancer dataset were predicted to be associated with "cancer" by FATHMM." (PMID 33318575, 2020). "Further, our combined prognosis showed that the combined high expression of SP5, FOXP1, ROBO1, DPP4, CDYL2, and STAMBPL1 is associated to patients’ better clinical prognosis of patients with lung cancer." (PMID 32552834, 2020). "About 89% of ROBO1, 76% of ROBO4, and 83% of SLIT2 variants of non-lung cancer dataset were predicted to cause a "decrease" in protein stability." (PMID 33318575, 2020). "Out of 825 variants; 34 in ROBO1, 57 in SLIT2, and 34 in ROBO4 were reported to be associated with lung cancer." (PMID 33318575, 2020). "Steric clash-induced destabilisations, primarily found in variants involving bulky amino acids were 7 in ROBO1, 5 in ROBO4 and 9 in SLIT2 from the lung cancer dataset." (PMID 33318575, 2020). "In comparison, the other 255 variants in ROBO1, 324 variants in SLIT2 and 121 variants in ROBO4 were considered as non-lung cancer dataset." (PMID 33318575, 2020). "About 25% of ROBO1, 25% of ROBO4, and 35% of SLIT2 variants of non-lung cancer dataset were predicted to be "Disease-related" by SNPs&GO." (PMID 33318575, 2020). "In comparison to, 9 variants in ROBO1, variants in ROBO4, and 34 variants from the non-lung cancer dataset were found." (PMID 33318575, 2020). "The variants were analysed in PROVEAN41 that predicted nearly 50% of ROBO1, 29% of ROBO4, and 63% of SLIT2 variants of lung cancer dataset to be "deleterious"." (PMID 33318575, 2020). "Myo9b is overexpressed in lung cancer tissue, and it interacts with ROBO1-ICD through its RhoGAP domain, which suppresses the Myo9b RhoGAP activity." (PMID 33318575, 2020). "miR-365a-3p enhance the migration and invasion of lung cancer cells by inhibiting ubiquitin specific peptidase 33 (USP33)/ slit guidance ligand 2 (SLIT2)/ roundabout guidance Receptor 1 (ROBO1) signaling pathway." (PMID 32595638, 2020).
lung carcinoma (continued). "USP33 deubiquitinates ROBO1 in lung cancer cells to maintain its stability, thereby regulating SLIT2 activity and inhibiting cancer cell metastasis." (PMID 29743814, 2018). "The miR-365/USP33/SLIT2/ROBO1 axis, a new mechanism, was reported to inhibit the invasion and metastasis of lung cancer." (PMID 29743814, 2018). "Our elucidation of the mechanism by which miR-365a-3p mediates the USP33/SLIT2/ROBO1 signalling pathway in lung carcinogenesis thus provides a new strategy for the diagnosis and targeted therapy of lung cancer." (PMID 29743814, 2018). "MiR-218 inhibited the migration and invasion of lung cancer cells through regulating Robo1 expression." (PMID 28738960, 2017). "On the contrary, ROBO1 behaves as tumor promotor in some other maligancies like lung cancer, in which high expression of ROBO1 is suggested as an independent player promoting brain metastasis." (PMID 28977866, 2017). "USP33 regulates Slit signaling by stabilizing Robo1 and is required for Slit inhibition of lung cancer cell migration." (PMID 24981056, 2014). "Data in this study show that USP33 interacts and stabilizes Robo1 protein level in lung cancer cells by inhibiting degradation via the ubiquitin proteasome pathway." (PMID 24981056, 2014). "Interestingly, MYO9B was shown to physically interact with the intracellular domain of Robo1 in lung cancer cells, leading to MYO9B inhibition and RhoA activation upon Slit addition." (PMID 37675403, 2023). "Another study showed that Robo1 was also a cancer-promoting gene that might promote the development and progression of lung cancer and lung cancer brain metastasis." (PMID 35477385, 2022). "Similarly, for outside the docking domains, 3 variants of ROBO1 and 2 variants of ROBO4 show inter-orbital shift of mutant amino acid residue compared to wild type residue in the lung cancer dataset." (PMID 33318575, 2020). "Our study is the first report that involves the characterisation of somatic variants of ROBO1.IG1, ROBO4.IG1-2 and SLIT2.D2 domains reported in various cancers including lung cancer, and their role in domain-domain interactions of the receptors (ROBO1.IG1 and ROBO4.IG1-2) and the ligand (SLIT2.D2)." (PMID 33318575, 2020). "Our study is the first report on the impact of cancer-associated missense variants on ROBO1/4 and SLIT2 interactions that might be the drivers of lung cancer progression." (PMID 33318575, 2020). "Interestingly, iMUTANT 2.0 revealed 91% of ROBO1, 79% of ROBO4, and 84% of SLIT2 variants of lung cancer dataset to cause a "decrease" in protein stability." (PMID 33318575, 2020). "Similarly, analysis in SIFT42 revealed about 65% of ROBO1, 47% of ROBO4, and 60% of SLIT2 variants of lung cancer dataset to be "damaging"." (PMID 33318575, 2020). "Similarly, 40% of ROBO1, 18% of ROBO4, and 56% of SLIT2 variants of non-lung cancer dataset were predicted to be "deleterious" by PROVEAN." (PMID 33318575, 2020). "However, 2 variants of ROBO1.IG1, 2 variants of SLIT2.D2 and 1 variant of ROBO4.IG1-2 domains in lung cancer dataset and 6 variants in SLIT2.D2 in the non-lung cancer dataset exhibits an intra-orbit amino acid position shift compared to wild types." (PMID 33318575, 2020). "It has been reported that the USP33/SLIT2/ROBO1 signalling pathway inhibits the migration of cancer cells; therefore, we hypothesised that miR-365a-3p downregulates this pathway to promote lung cancer progression." (PMID 29743814, 2018). "In summary, we not only confirmed that miR-365a-3p targets and downregulates USP33 in lung adenocarcinoma, but we also further confirmed that miR-365a-3p promotes the proliferation, migration, and invasion of lung cancer cells by downregulating the USP33/SLIT2/ROBO1 pathway." (PMID 29743814, 2018). "In lung cancer, SLIT2/ROBO1 suppressed cancer cell migration through regulating the Myo9b/RhoA pathway." (PMID 35615148, 2022).
lung carcinoma (continued). "Finally, for the interacting domains, the prioritisation analysis revealed 2 variants of ROBO1, 2 variants of ROBO4 and 3 variants of SLIT2 in lung cancer dataset and 6 variants of ROBO1, 2 variants of ROBO4 and 15 variants of SLIT2 from the non-lung cancer dataset as depicted in." (PMID 33318575, 2020). "Our current work shows that in lung cancer cells, USP33 also interacts with Robo1 and is required for Slit signaling in inhibiting lung cancer cell migration." (PMID 24981056, 2014). "SCAN-ACT identified 174 monospecific CAR-T targets in GBM, including several established GBM CAR-T targets such as CD276, EGFR, IL13RA2, ROBO1, as well as targets studied in different diseases like GPC2 in neuroblastoma, IL11RA in osteosarcoma, or DLL3 in lung cancer." (PMID 40814001, 2025). "Thus, in this study, we aimed to elucidate the role of miR-365a-3p in lung cancer cells and the relationship among miR-365a-3p, USP33, SLIT2, and ROBO1 in lung adenocarcinoma." (PMID 29743814, 2018). "Downregulation of USP33 reduces the protein stability of Robo1 in lung cancer cells, providing a previously unknown mechanism for USP33 function in mediating Slit activity in lung cancer cells." (PMID 24981056, 2014). "Both Slit2-WT and Slit2-ΔE15 inhibit lung cancer cell invasion, but Robo4 is essential for Slit2-WT-mediated invasion inhibition in CL1-5 cells, while neither Robo1 nor Robo4 is required for Slit2-ΔE15-mediated invasion inhibition." (PMID 41227302, 2025).
colorectal cancer (17 papers, 2012 to 2024). A primary or metastatic malignant neoplasm that affects the colon or rectum. "The same mutation of ROBO1 also occurred in colorectal cancer cell line HT115 according to the COSMIC database." (PMID 35615148, 2022). "Multiple correlated SNPs in intron 1 of the ROBO1 gene were suggestively associated with the breast-colorectal cancer phenotype in the discovery and replication data (most significant; rs7430339, Pdiscovery = 1.2E-04; rs7429100, Preplication = 2.8E-03)." (PMID 29698419, 2018). "Slit2 (slit guidance ligand 2), a ligand of the Roundabout1 (Robo1) transmembrane receptor, is often overexpressed in colorectal carcinomas (CRCs)." (PMID 31242633, 2019). "However, since germline variation in the region of ROBO1 was suggestive of an association with breast-colorectal cancer risk, and given mounting evidence for the role of ROBO1 as a tumor suppressor gene, further investigation of this association may be warranted." (PMID 29698419, 2018). "In colorectal carcinoma cells, Slit2/Robo1 signaling promotes degradation of E-cadherin, EMT, tumor growth and metastasis." (PMID 29141914, 2018). "Using cDNA microarray, a significant upregulation of ROBO1 was found in colorectal carcinoma tissues." (PMID 26674478, 2015). "In colorectal carcinoma patients, the overexpression of SLIT2 and ROBO1 was significantly associated with an increased metastatic risk and poorer overall survival in colorectal carcinoma patients." (PMID 26674478, 2015). "Although the involvement of Slit2/Robo1 signaling in tumor development has been widely implicated, the biological significance and molecular mechanisms of Slit2/Robo1 signaling in the initiation of colorectal carcinoma are largely undetermined." (PMID 25605242, 2015). "Our main findings include a suggestive association of a cluster of SNPs in ROBO1 with the breast-colorectal cancer phenotype, although none of the SNPs were genome-wide statistically significant." (PMID 29698419, 2018). "A similar model with co-occurrences of mutation and loss of expression of ROBO1 and ROBO2 has been reported in colorectal cancers, supporting our speculation." (PMID 26608094, 2015). "Here, we employed several complementary mouse models of intestinal cancers, including the Slit2 transgenic mice, the ApcMin/+ spontaneous intestinal adenoma mouse model, and the DMH/DSS-induced colorectal carcinoma model to clarify function of Slit2/Robo1 signaling in intestinal tumorigenesis." (PMID 25605242, 2015). "This led us to speculate that the Slit2/Robo1 signaling pathway may likely regulate Wnt/β-catenin signaling and thereby promote the initiation of colorectal carcinoma." (PMID 25605242, 2015). "The coincidental activation of Slit2/Robo1 signaling and Src in colorectal carcinoma led us to hypothesize that a potential interaction between the Slit2/Robo1 and Src signaling may be an important mechanism involved in the activation of Wnt/β-catenin signaling." (PMID 25605242, 2015). "Furthermore, Slit2 and Robo1 promote degradation of ECad and expression of EMT markers in human colorectal carcinoma cell lines, suggesting that this regulation is conserved between flies and mammals." (PMID 33968921, 2021).